CXCL5 (C-X-C motif chemokine ligand 5)
Diseases named in the same sentence as CXCL5 in open-access papers (continued):
Sharing a sentence is not in itself a finding about the gene and the disease.
pancreatic cancer (continued). "We found that Cxcl5 deletion restricted pancreatic tumor growth in a 3D spheroid-in-Matrigel culture system without affecting cancer cell growth in 2D culture." (PMID 40050422, 2025). "CXCR2 and its ligands, such as CXCL5, are crucial for TAN recruitment in pancreatic cancer." (PMID 40443678, 2025). "Furthermore, CXCL5 was found to have a similar effect on 3D tumor growth in the mouse colon cancer cell line MC38, the human pancreatic cancer cell lines MIA PaCa-2 and PANC-1, and the human lung cancer cell line A549." (PMID 40050422, 2025). "Racial and ethnic variation is apparent for neutrophil- and stress-linked cytokine biomarkers ENA-78/CXCL5 and GRO-α/CXCL1, independent of CCa or pancreas tumor type." (PMID 39989973, 2025). "Additionally, the higher expression of the human homolog of mouse Cxcl5, CXCL6, and other ligands of CXCR2 (CXCL1 and CXCL2) was also identified in human pancreatic cancer cells after adding AMP." (PMID 37867243, 2023). "In addition to protein levels, NSD3 induces global H3K36 dimethylation in pancreatic cancer cells and influences the mRNA levels for genes including ADAM28, ADAM9, BIRC3, CXCL5, DUOX2, GABRP, ITGB6, and RAB11FIP1." (PMID 37062069, 2023). "CXCL5, a CXCR2 ligand, are significantly elevated in pancreatic cancer and can recruit TANs." (PMID 36324574, 2022). "CXCL5, a ligand of CXCR2, induces angiogenesis in pancreatic cancer." (PMID 36324574, 2022). "Similar to pancreatic carcinoma, in prostate cancer, YAP activation also promotes the secretion of a protumorigenic chemokine, C-X-C motif chemokine ligand 5 (CXCL5), which is responsible for Cxcl5–Cxcr2-mediated MDSC recruitment, thus impeding T cell proliferation." (PMID 34205830, 2021). "Moreover, expression of the receptor for CXCL5, C-X-C-motif chemokine receptor-2 (CXCR2), was upregulated in pancreatic cancer cells." (PMID 31999765, 2020). "Thus, elevated CXCL5 protein levels have been reported in CRC patients and in human pancreatic cancer cell lines." (PMID 18578857, 2008). "Thus, while CXCL5 appears to have multiple positive effects acting as a chemoattractant to promote PDAC tumorigenesis, it also appears to function in an autocrine manner, increasing pancreatic cancer cell fitness and viability." (PMID 38339310, 2024). "Based on the existing literature and our experimental results, we hypothesized that KRT7 and KRT19 are involved in EMT as epithelial components, while CXCL5 and IGF2BP3 act as regulatory factors to regulate EMT, thereby promoting the invasion and metastasis of pancreatic cancer." (PMID 37371833, 2023). "Although CXCL5 inhibitors have not yet been tested in cancer patients, their blockade of neutrophil recruitment and anti-angiogenesis actions provide a direction for the future treatment of pancreatic cancer patients." (PMID 36324574, 2022). "Analysis of the gene expression profile of 69 pancreatic tumor tissues and 61 adjacent nontumor tissues in the GSE62452 database, revealed that the expression of CXCL5 was significantly higher in pancreatic cancer tissues than in adjacent nontumor tissues (p<0.0001, Mann-Whitney U test)." (PMID 32201508, 2020). "ENA-78/CXCL5 and GRO-α/CXCL1 are of particular interest, as they are upregulated in NHB patients independent of CCa status and pancreas tumor type." (PMID 39989973, 2025). "ENA-78/CXCL5 and GRO-α/CXCL1 have been shown to have increased expression in tumors of patients with malignant versus non-malignant pancreas tumors, suggesting a role for these genes in pancreatic carcinogenesis." (PMID 39989973, 2025).
colorectal cancer (51 papers, 2008 to 2025). A primary or metastatic malignant neoplasm that affects the colon or rectum. "The chemokine CXCL5 enhances the activation of Snail causing EMT to induce invasion of colorectal cancer." (PMID 35898399, 2022). "The expression levels of CXCL5 in colorectal cancer tissues are also found to be associated with malignant phenotypes of prostate cancer." (PMID 33458757, 2021). "(2017) found that CXCL5 was overexpressed in tumor tissue and associated with poor prognosis in colorectal cancer patients." (PMID 30451357, 2019). "The activation of the ERK/ELK1/Snail signaling pathway underlies the promotive function of tumor-derived CXCL5 in colorectal cancer metastasis." (PMID 31772143, 2019). "We found that CXCL5 was overexpressed in tumor tissues and associated with advanced tumor stage as well as poor prognosis in colorectal cancer patients." (PMID 28356111, 2017). "Studies have confirmed that high levels of CXCL5 are associated with high metastatic potential and poor survival rates in prostate cancer, colorectal cancer, hepatocellular carcinoma, and oral squamous cancers." (PMID 23469080, 2013). "Interestingly, it has been reported that low expression of CXCL5 is significantly associated with poor prognosis for patients with colorectal cancer." (PMID 32337262, 2020). "Moreover, low CXCL5 expression was associated with more aggressive tumor growth and ability to metastasize in a rat model of colorectal cancer and a poor prognosis in patients." (PMID 28923105, 2017). "Thus, we observed for the expression levels of CXCL8, CXCL1 and CXCL5 a significant association with the development of colorectal carcinoma and also CRLM." (PMID 18578857, 2008). "In colorectal cancer, CXCL5 mediates epithelial-mesenchymal transition (EMT) by activating the ERK/Elk-1/Snail and AKT/GSK3β/β-catenin signaling pathway, which promotes tumor cell migration and invasion and liver metastases." (PMID 40313933, 2025). "MiR-432-5p repressed colorectal cancer cell growth and invasion through regulating CXCL5 expression." (PMID 39192374, 2024). "As there are only a few studies concerning the concentration of CXCL5 in the course of human colorectal cancer, we decided to focus alsoon the studies regarding tissue and gene expression, and studies on CXCL5 in other species." (PMID 37848726, 2023). "We indicated that the serum concentration of CXCL5 was statistically higher in the group of colorectal cancer patients when compared to healthy controls (p = 0.01)." (PMID 37848726, 2023). "Regarding regulatory role of CXCL5 in tumors, an existing study demonstrated that in colorectal cancer, CXCL5 fosters FOXD1 expression mediated through the AKT/NF-κB pathway to induce angiogenesis." (PMID 35936390, 2022). "CXCL5 induces tumor angiogenesis in colorectal cancer by enhancing FOXD1 expression mediated by the AKT/NF-κB pathway." (PMID 35936390, 2022). "CXCL5 as a tumor angiogenic factor promoted the expression of FOXD1 by activating the AKT/NF-κB pathway in colorectal cancer." (PMID 34987577, 2021). "CXCL5 is a predictor of poor prognosis in patients with colorectal cancer, and blocking the CXCL5- CXCR2 axis is an effective treatment strategy for them." (PMID 33955820, 2021). "It has been reported that the CXCL5 chemokine enhances the migratory and invasive properties of colorectal cancer cells by inducing epithelial-mesenchymal transition." (PMID 34781983, 2021). "Along these lines, CXCL5 that was secreted by CAFs promoted the expression of PD-L1 by several colorectal cancer cell lines; here, CXCL5 signals were transferred through CXCR2, leading to PD-L1 up-regulation via a PI3K-dependent process." (PMID 32582148, 2020). "In conclusion, our findings support CXCL5 as a promoter of colorectal cancer metastasis and a predictor of poor clinical outcomes in colorectal cancer patients." (PMID 28356111, 2017).
colorectal cancer (continued). "The elevated expression of CXCL5 can also potentiate the metastasis of colorectal cancer cells to the liver in vivo in nude mice intrasplenic injection model." (PMID 28356111, 2017). "CXCL5 has been reported to be up-regulated in malignant tumors, such as nasopharyngeal and colorectal cancer, and to be closely correlated with a poor prognosis." (PMID 26503598, 2015). "CXCL5 was also suggested to serve as a novel predictive marker for prognosis determination of many cancers, such as colorectal cancer." (PMID 25011526, 2014). "For example, CXCL5 is overexpressed in oral squamous cell carcinoma, colorectal cancer, hepatocellular cancer, prostate cancer, gastric cancer and pancreatic cancer, with overexpression being associated with poor patient survival." (PMID 23469080, 2013). "Levels of CCL2, CXCL1 and CXCL5 were consistently higher than those of VEGF (a current therapeutic target in colorectal cancer) in all patients examined." (PMID 22125641, 2011). "In addition, cytokine array and ELISA analysis of serum from cancer patients and healthy volunteers found that CXCL5 levels are a prognostic marker for colorectal cancer." (PMID 41392310, 2025). "They concluded that CXCL5 may serve as a promoter of colorectal cancer metastasis and a predictor of poor clinical outcomes in colorectal cancer patients and inhibition of the CXCL5/CXCR2 signaling pathway may be a promising target for CRC therapy." (PMID 37848726, 2023). "Previous studies revealed that in melanoma and colorectal carcinoma, CAFs could release C-X-C motif chemokine ligand 5 (CXCL5), which binds to the C-X-C motif chemokine receptor 2 (CXCR2) on cancer cells." (PMID 38111465, 2023). "To improve the diagnostic capacity of serum biomarkers for colorectal cancer (CRC), we introduced three novel indicators, namely, the C-X-C motif chemokine ligand 5 (CXCL5), stanniocalcin 2 (STC2), and chitinase 3 like 1 (CHI3L1) and assessed their performances in the detection of CRC." (PMID 35646113, 2022). "In colorectal cancer, CXCL5 promoted tumor angiogenesis via the AKT/NF-κB pathway." (PMID 34194499, 2021). "Here, we examined the effect of CXCL5 on tumor angiogenesis in colorectal cancer (CRC)." (PMID 30792394, 2019). "Additionally, the CXCL5/CXCR2 axis has also been found to enhance human colorectal cancer metastasis through the activation of the ERK/Elk-1/Snail and AKT/GSK3β/β-catenin pathways." (PMID 29665837, 2018). "Immunohistochemistry was used to detect expression of CXCL5 in colorectal cancer patients tissues." (PMID 28356111, 2017). "In addition, CXCL5 may be a potential prognostic indicator for many cancers, like prostate cancer, lung cancer, and colorectal cancer." (PMID 35936390, 2022). "It was reported that CXCL5 could induce angiogenesis of colorectal cancer via upregulating FOXD1." (PMID 35504887, 2022). "However, CXCL5 inhibits tumor progression in colorectal cancer and renal cell carcinoma." (PMID 33955820, 2021). "Moreover, colorectal cancer cells has been reported to secret CXCL5, which could promote cell proliferation and migration as well as invasion." (PMID 33061849, 2020). "However, in colorectal cancer, the effect of CXCL5 may likely depend on an autocrine signalling pathway." (PMID 29665837, 2018). "Additionally, overexpression of CXCL5 enhanced the migration and invasion of colorectal cancer cells by inducing the epithelial-mesenchymal transition (EMT) through activation of the ERK/Elk-1/Snail pathway and the AKT/GSK3β/β-catenin pathway in a CXCR2-dependent manner." (PMID 28356111, 2017). "There is evidence that the upregulation of NOX4, CXCL8, CXCL5, GDF15, and MMP13 genes in colorectal cancer promotes the metastasis of cancer cells, so a sustained upregulation of these genes after aspirin treatment will not benefit from treatment." (PMID 41425852, 2025).
colorectal cancer (continued). "That is why the aim of our study was an effort to elucidate and evaluate the utility of selected CXC-chemokines determination (CXCL5, CXCL14 and CXCL16) in patients with colorectal cancer compared to healthy control." (PMID 37848726, 2023). "For example, in colorectal cancer tissue, CXCL1, CXCL2, CXCL3, CXCL5, CXCL8, and CXCL11 were highly expressed, while CXCL12, CXCL13, and CXCL14 were little expressed." (PMID 36612163, 2022). "The close interplay among these mediators is demonstrated by the up-regulation of CXCL5 and CXCL8 expression in human non-small cell lung cancer cells and of CXCL1 in colorectal cancer cells induced by PTGS2." (PMID 31920649, 2019). "Our study also showed that our colorectal cancer patients explant tissue secreted high levels of CCL2, CXCL1 and CXCL5, compared to VEGF." (PMID 22125641, 2011). "Additionally, all utility values of the newly tested parameters (CXCL5, CXCL14) were greater than those obtained for CA 19–9, which suggests their higher utility than this routine marker for colorectal cancer patients." (PMID 37848726, 2023). "Similarly, we found recently that apoptotic colorectal cancer cells secrete CXCL1, CXCL5, and CXCL8 in response to chemotherapeutic drugs such as oxaliplatin, 5-FU, or bortezomib." (PMID 37957750, 2023). "Lastly, we noted an upregulation of CXCL5/ENA-78 under many of the treatment conditions across several cell lines, which may induce colorectal cancer angiogenesis." (PMID 34611474, 2021). "Additionally, CXCL5 has been demonstrated to possess the ability to activate the PI3K-AKT signalling pathway in hepatocellular carcinomas and colorectal cancer cells via its receptor CXCR2." (PMID 29665837, 2018). "Additionally, although we centered our investigation on the CXCL5/CXCR2 axis as a primary signaling pathway, it's crucial to recognize that other signaling cascades may also contribute to colorectal cancer progression." (PMID 38817853, 2024). "In addition, CXCL5 is positively correlated with the micro-vessel marker CD31, and it activates the AKT/NF-kB/FOXD1/VEGF-A pathway to enhance its tube formation ability in a CXCR2-dependent manner in colorectal cancer." (PMID 36980564, 2023).
melanoma (42 papers, 2011 to 2025). A malignant, usually aggressive tumor composed of atypical, neoplastic melanocytes. "As we previously reported, baseline serum CXCL5 is associated with the efficacy of nivolumab in advanced melanoma and increased serum levels of CXCL5 correlated significantly with irAEs from nivolumab." (PMID 31417907, 2019). "In addition, CXCL5 from cancer-associated fibroblasts increases PD-L1 expression in melanoma and colorectal cancer cells." (PMID 32632106, 2020). "In a study conducted by Taku and colleagues, 46 patients with advanced melanoma who were treated with nivolumab were examined for their serum sCD163 and CXCL5 levels." (PMID 38169638, 2024). "A375 melanoma cells were stimulated with LL-37, and the mRNA expression of CXCL5, IL23A, MMP1, and MMP9 were evaluated in vitro." (PMID 36980564, 2023). "CXCL5 also plays a key role in lymphangiogenesis in melanoma, which can be inhibited by blocking the CXCR2 receptor." (PMID 35504887, 2022). "For example, CAF-secreted CXCL5 was involved in the expression of PD-L1 on mouse melanoma and colorectal tumor cells in a phosphatidylinositol 3-kinase (PI3K)/AKT-dependent manner." (PMID 36338519, 2022). "For example, POSTN from CAFs stimulates TAMs to produce CXCL5 to enhance PD-L1 expression in TAMs, maintaining regulatory T cells in melanoma." (PMID 35409404, 2022). "CXCL5 expression was positively associated with the risk of metastasis in bladder cancer, NSCLC, and melanoma." (PMID 35150082, 2022). "Under the influence of CXCL5-overexpressing CAFs, melanoma cells displayed an elevated level of PI3K/AKT activation and PD-L1 expression in a CXCR2-dependent way." (PMID 33430277, 2021). "In a spontaneous melanoma mouse model, C-X-C motif chemokine ligand 5 (CXCL5) induces recruitment of CXCR2+ MDSCs to the primary tumor." (PMID 34359674, 2021). "As an important chemokine, C-X-C motif chemokine ligand 5 (CXCL5) is a critical factor in the distant metastasis of various tumors including melanoma, and the role of CXCL5 in tumor metastasis depends on neutrophils." (PMID 33042821, 2020). "Tumor-expressed CXCL5 in melanoma has also been found to drive tumor lymphangiogenesis and lymphogenous metastasis through CXCR2 expressed on LECs." (PMID 31105685, 2019). "Neutrophils migrate into melanoma using the CXCR2 chemokine receptor in response to its ligands CXCL1, CXCL2, and CXCL5 expressed in melanoma." (PMID 30899263, 2019). "The sensitivity and specificity of the baseline serum CXCL5 in advanced melanoma were 70.6 and 69.0%, respectively (p = 0.0016)." (PMID 31080803, 2019). "High baseline serum levels of CXCL5 were correlated with objective response to nivolumab in patients with advanced melanoma." (PMID 31080803, 2019). "In this report, we further analyzed the serum levels of sCD163 and CXCL5 in 46 cases of advanced melanoma treated with nivolumab." (PMID 29643991, 2018). "In this report, we analyzed the serum levels of sCD163 and CXCL5 in 46 cases of advanced melanoma treated with nivolumab." (PMID 29643991, 2018). "The purpose of this study was to evaluate the value of using serum levels of sCD163 and CXCL5 to predict irAEs in patients with advanced melanoma who were administered nivolumab." (PMID 29643991, 2018). "Increased serum levels of sCD163 and CXCL5 correlate not only with autoimmune diseases such as atherosclerosis and rheumatoid arthritis, but also with adverse events in melanoma patients treated with nivolumab." (PMID 29050354, 2017). "Since IL-23p19 plays important roles in inducing Th17 cell proliferation even in the cancer microenvironment, increased levels of CXCL5 in parallel with IL-23p19 by LL-37 could trigger angiogenesis, leading to local invasion of melanoma in the primary lesion." (PMID 36980564, 2023).